GAS5 (growth arrest specific 5)
Synonyms: SNHG2; NCRNA00030
Gene: Long non-coding RNA gene on chromosome 1 (173,851,424 to 173,868,940, reverse strand). Ensembl gene ENSG00000234741.
Gene Ontology:
Biological process: RNA processing
Cellular component: nucleolus
Diseases named in the same sentence as GAS5 in open-access papers:
GAS5 is named in the same sentence as 267 diseases in open-access papers, as found by Europe PMC text mining. Sharing a sentence is not in itself a finding about the gene and the disease. The quoted sentences say what the papers report.
breast carcinoma (158 papers, 2011 to 2026). "Initially identified as a downregulated transcript in breast cancer in 2009, GAS5 has since emerged as both a diagnostic biomarker and a promising therapeutic target." (PMID 40521240, 2025). "To further explore the mechanism underlying the low expression of GAS5 in breast cancer, we focused on m6A modification, which has been reported to play an important role in the progression of multiple tumors." (PMID 38782769, 2024). "In breast cancer, low GAS5 expression is associated with clinical characteristics, and restrains breast cancer progression." (PMID 38782769, 2024). "In contrast, expression of the lncRNA GAS5 is diminished in many forms of breast cancer, and its loss is associated with the incidence and progression of breast cancer." (PMID 38189818, 2024). "A stem-loop structure encoded in GAS5 exon 12 which serves as GRE-mimic was found to induce apoptosis in breast cancer cells." (PMID 35736636, 2022). "XIAP can be indirectly suppressed by GAS5 and, in luminal breast cancer, is associated not only with apoptosis but also with autophagy." (PMID 34202777, 2021). "The gene encoding suppressive lncRNA GAS5 harbors a promoter CpG island, and GAS5 expression level is also regulated epigenetically through the participation of promoter methylation in breast cancer." (PMID 34202777, 2021). "The authors found that the lower expression level of GAS5 in breast cancer was associated with an advanced TNM stage, histological grading, metastasis, poor survival, and trastuzumab resistance." (PMID 34202777, 2021). "Nowadays, several lncRNAs have been shown to modify critical breast cancer associated molecular pathways such as GAS5." (PMID 33585557, 2020). "Increasing data showed that abnormal expression of GAS5 is involved in many kinds of cancers and its aberrant expression is associated with lung cancer, renal cell carcinoma, breast cancer, glioblastoma, and CRC." (PMID 30902880, 2019). "Nucleofection of a plasmid encoding mature GAS5 lncRNA induces apoptosis in hormone-sensitive and -insensitive breast cancer cell lines, and wild-type HREM sequence is required for this activity." (PMID 26862727, 2016). "Kaplan–Meier survival estimates showed that low GAS5 expression in breast cancer tissues was associated with poor disease free survival (DFS) (P = 0.015, log-rank test) and overall survival (OS) (P = 0.048, log-rank test)." (PMID 27034004, 2016). "Several lines of evidence indicated that GAS5 was implicated and aberrantly expressed in multiple cancers, such as breast cancer, hepatocellular carcinoma, gastric cancer, bladder cancer and non-small-cell lung cancer (NSCLC)." (PMID 26511107, 2015). "Decreased expression of RNU44, a snoRNA derived from GAS5 is associated with more aggressive tumors in breast cancer and head and neck squamous cell carcinoma." (PMID 25400658, 2014). "For example, Gas5 was shown to be involved in the regulation of cell death and proliferation in breast cancer, and its reduced expression was associated with poor prognosis in the studied patients." (PMID 23991050, 2013). "In fact, the expression of GAS5 (growth arrest specific 5), a gene which encodes an lncRNA but also harbors ten intronic snoRNAs, is downregulated in breast cancer compared to normal adjacent epithelial breast tissue." (PMID 23965974, 2013). "The non-coding growth arrest specific transcript 5 gene (GAS5), which encodes multiple snoRNAs, induces growth arrest and apoptosis in breast cancer cell lines, and is significantly downregulated in breast cancer." (PMID 21407217, 2011). "Their function is not well understood, but recent reports suggest that the noncoding growth arrest-specific transcript 5 gene (GAS5), which encodes multiple snoRNAs, is significantly downregulated in breast cancer." (PMID 22074333, 2011). "Likewise, GAS5 rs145204276 deletion allele was associated with a lower risk of breast cancer, and a lower risk of lymph node metastasis in prostate cancer." (PMID 35736636, 2022).
breast carcinoma (continued). "However, few studies have examined the effect of GAS5 on the various processes associated with breast cancer metastasis." (PMID 34202777, 2021). "Moreover, a recent study showed that an insertion (ins)/deletion (del) polymorphism located within the GAS5 promoter (rs145204276 AGGCA/–) affects the risk of breast cancer." (PMID 32486413, 2020). "Our study provided the first evidence that the deletion allele of GAS5 rs145204276 may have a protective role in mediating individual susceptibility to breast cancer." (PMID 33369471, 2020). "The association between GAS5 and miRNAs has been widely studied in breast cancer." (PMID 33076450, 2020). "The aim of this case-control study was to explore whether growth arrest-specific 5 (GAS5) lncRNA 5-bp Ins/Del (rs145204276) polymorphism is involved in the breast cancer susceptibility." (PMID 33369471, 2020). "An lncRNA GAS5 was found to be suppressed in breast cancer tissue and cell lines, which was associated with larger tumor size, advanced metastasis, and poorer clinical phenotype of breast cancer." (PMID 30577536, 2018). "The tumor suppressive role of GAS5 is supported by the identification of genetic susceptibility of its genomic locus, 1q25, to several cancers, including melanoma, prostate cancer, breast cancer, colorectal cancer and B-cell lymphoma." (PMID 24013378, 2013). "Finally, the lncRNA GAS5 has also been linked to trastuzumab resistance in breast cancer." (PMID 28430163, 2017). "Thus, GAS5 may be explored as a prognostic and diagnostic molecule in trastuzumab-resistant breast cancer patients." (PMID 29299178, 2017). "The overexpression of GAS5 resulted in a reduced survival rate of breast cancer cell lines, as well as a decrease in the size of tumors in mice, whereas the inhibition of GAS5 displayed an opposite effect." (PMID 39941145, 2025). "Beyond breast cancer, GAS5 is frequently downregulated across a broad spectrum of malignancies, where its loss is associated with dysregulation of cell cycle control, an event that can critically contribute to tumour development and progression." (PMID 40521240, 2025). "GAS5 in radiation therapy holds great promise to improve the outcomes in treatment, and in the case of breast cancer, it sensitizes cells to ionizing radiation by inhibiting miR-21-mediated DNA repair pathways." (PMID 39958058, 2025). "GAS5 can promote apoptosis in breast cancer through several signaling pathways, such as cell-death-receptor-mediated signaling pathways." (PMID 40006021, 2025). "MALAT1, UCA1, CYTOR, HOTAIR, and GAS5 expressions were compared between breast cancer patients treated with tamoxifen alone (control) and those treated with tamoxifen plus NanoCurcumin (target group)." (PMID 41031251, 2025). "Although GAS5 or growth arrest specific 5 lncRNA was downregulated in circulating NK cells isolated from peripheral blood of breast cancer patients with fold change of 0.43, this difference was, however, statistically insignificant (P = 0.1984)." (PMID 40781182, 2025). "Among the numerous lncRNAs implicated in drug resistance, MALAT1, UCA1, CYTOR, and HOTAIR have emerged as crucial oncogenes, and GAS5 is a well‐known lncRNA that acts as a tumor suppressor in breast cancer." (PMID 41031251, 2025). "Elevated GAS5 levels correlate with reduced TCA flux, which is associated with favorable clinical outcomes in patients with breast cancer." (PMID 40804479, 2025). "Elevated expression of GAS5‐derived transcripts postchemotherapy correlates with enhanced apoptosis and reduced survival in breast cancer cells, highlighting its therapeutic implications." (PMID 40584410, 2025). "For instance, the growth-arrest-specific gene 5 (GAS5) is significantly upregulated in women with breast cancer and regulates the expression of various oncogenic genes." (PMID 40006021, 2025).
breast carcinoma (continued). "Through epigenetic and other regulatory mechanisms, GAS5 has been shown to enhance drug sensitivity, improve prognosis, and promote apoptosis in breast cancer." (PMID 41226688, 2025). "Prior studies have demonstrated that GAS5 inhibits breast cancer progression through adsorbing distinct miRNAs (e.g., miR-221-3p, miR-196a-5p, miR-378a-5p, miR-23a, and miR-103) as an miRNA sponge and further up-regulating miRNA target proteins." (PMID 38782769, 2024). "Overexpression of GAS5 inhibited the proliferation of breast cancer cells, while knockdown of GAS5 promoted the proliferation of breast cancer cells." (PMID 38782769, 2024). "Downregulation of GAS5 (growth arrest-specific 5) on the other hand can significantly promote trastuzumab resistance in breast cancer." (PMID 38668383, 2024). "In a cell culture study, a doxorubicin-resistant breast cancer cell model (MCF-7/ADR) was also found to express significantly higher levels of ABCB1 but lower levels of GAS5 than the drug-sensitive MCF-7 parental cells." (PMID 39403602, 2024). "GAS5 has been proven to inhibit breast cancer as a tumor suppressor through a variety of functions and mechanisms." (PMID 38782769, 2024). "GAS5 regulated by FTO-mediated m6A modification represses the growth of breast cancer via the IGF2BP2/QKI pathway, suggesting that the FTO/GAS5/IGF2BP2/QKI pathway can be a potential target for breast cancer treatment." (PMID 38782769, 2024). "We first analyzed GAS5 expression in breast cancer through UALCAN database, and found that GAS5 was downregulated in breast cancer tissues compared with that in normal tissues." (PMID 38782769, 2024). "In the present study, we found that GAS5 suppressed the growth of breast cancer cells by interacting with IGF2BP2." (PMID 38782769, 2024). "GAS5 suppressed breast cancer growth via IGF2BP2/QKI, and this inhibitory effect was modulated by FTO both in vitro and in vivo." (PMID 38782769, 2024). "Consistent with previous studies including those on breast cancer, we found that GAS5 was underexpressed in breast cancer tissues and cells." (PMID 38782769, 2024). "In the present study, we found that the expression of lncRNA GAS5 was decreased in breast cancer and regulated by FTO-mediated m6A modification." (PMID 38782769, 2024). "For instance, the lncRNA GAS5, a tumor suppressor that is down-regulated in mammary carcinoma, has 20 targets in the lncRNA-mRNA network and 12 of these putative targets belong to the pathway “peptide chain elongation” (Bonferroni corrected p-value 3.23e-15)." (PMID 38838009, 2024). "The GAS5 promotes apoptosis in triple-negative breast cancer, which is highly metastatic breast cancer, by binding miR-378a." (PMID 36770654, 2023). "Previous studies have also shown that lncRNA GAS5, as a negative regulator of miR-21, is involved in the occurrence of osteoarthritis, breast cancer, osteosarcomas, and osteoporosis." (PMID 37821982, 2023). "In breast cancer (BC), GAS5 has mainly been described as tumor suppressor lncRNA capable of promoting apoptosis and inhibiting cell proliferation." (PMID 37444428, 2023). "In line with our findings, a previous study demonstrated a positive correlation between NEAT1 and GAS5 in breast cancer patients." (PMID 36439973, 2023). "The lncRNA GAS5 was discovered decades ago and has been predominantly studied in human cancer, particularly in breast cancer, where its downregulation is correlated with unfavorable clinical outcomes." (PMID 37444428, 2023). "The healthy breast epithelia abundantly express the LncRNA NKILA and long GAS5, but their low expression correlates with metastasis of breast cancer." (PMID 36770654, 2023). "Upregulated expression of the lncRNA GAS5 restrained cell viability and facilitated apoptosis of breast cancer cells, including triple-negative breast cancer cells." (PMID 37239407, 2023).
breast carcinoma (continued). "Another study revealed that lncRNA growth arrest-specific transcript 5 (GAS5) is a significant contributor to the pathogenesis of breast cancer." (PMID 36899946, 2023). "Aberrant GAS5 expression was reported in actively proliferating cancer cells including breast cancer, cervical cancer, colorectal cancer, gastric cancer, hepatocellular carcinoma, renal cell carcinoma, and glioma." (PMID 35736636, 2022). "As GAS5 expression was downregulated in irradiated breast cancer cells, we wanted to determine its role in the radiation response." (PMID 35059460, 2022). "The action mechanism indicated that GAS5 combined with miR-216b regulates the epithelial-mesenchymal transition of breast cancer tissues, promotes apoptosis, and weakens the invasion ability." (PMID 35837102, 2022). "In conclusion, we found that lncRNA GAS5 sensitized breast cancer cells to ionizing radiation by inhibiting DNA repair and suppressing miR-21, identifying novel targets for breast cancer radiosensitization." (PMID 35059460, 2022). "First, we found that GAS5 expression was downregulated not only in breast cancer cells but also in irradiated cells, indicating a radiation-responsive role of GAS5." (PMID 35059460, 2022). "In cancer, when GAS5 (another trans-regulatory lncRNA) is overexpressed in breast cancer cell lines, it can induce cell apoptosis and inhibit cell proliferation." (PMID 35813295, 2022). "In conclusion, our findings identify lncRNA GAS5 as a potential target for breast cancer radiotherapy and show that it exerts a role in DNA repair and apoptotic regulation." (PMID 35059460, 2022). "Among these lncRNAs, lncRNA GAS5 expression was shown to be downregulated in breast cancer and related to trastuzumab resistance." (PMID 35059460, 2022). "In this study, we found that lncRNA GAS expression was lower in breast cancer cells, and overexpression of GAS5 effectively enhanced the radiosensitivity of breast cancer cell lines." (PMID 35059460, 2022). "In previous literature, the level of GAS5 is decreased in various cancers including breast cancer and gastric cancer." (PMID 35456391, 2022). "lncRNA GAS5 was also found to mediate the regulatory effects of Notch signaling on breast cancer cells." (PMID 35059460, 2022). "Among all lncRNAs, lncRNA GAS5 was shown to have downregulated expression in breast cancer tissues and cell lines and was closely correlated with cancer growth and chemoresistance." (PMID 35059460, 2022). "In our study, we identified a potential interacting miRNA with GAS5, miR-21, and found that the GAS5-miR-21 axis contributed to the radiosensitivity of breast cancer cells." (PMID 35059460, 2022). "It has been shown that miR-378 regulates proliferation and cell cycle progression of gastric cancer cells by targeting GAPLINC lncRNA whereas modulates apoptosis by interacting with GAS5 lncRNA in breast cancer." (PMID 35814429, 2022). "Several reports have shown that the relative expression of GAS5 decreases in various types of cancer, such as cervical cancer, breast cancer, and esophageal squamous cell carcinoma, and also in the cisplatin-resistant lung cancer A549 cells." (PMID 36672566, 2022). "Among all these molecules, lncRNA GAS5 expression was proven to be downregulated in breast cancer and was found to be related to trastuzumab resistance." (PMID 35059460, 2022). "Downregulation of lncRNA GAS5 occurs in many cancers including breast cancer, non-small cell lung cancer, and colorectal cancer." (PMID 35435104, 2022). "A 2016 study noted that GAS5 was among the top 15 downregulated lncRNAs of HER2-positive breast cancer." (PMID 34202777, 2021). "Many experimental and clinical studies have revealed the functions of GAS5 in the biological processes of breast cancer." (PMID 34202777, 2021). "This study demonstrated the participation of GAS5 in inhibiting the growth and invasion of breast cancer cells by binding oncogenic miR-21 and activating its targets, such as PTEN and PDCD4." (PMID 34202777, 2021).